IL6 (interleukin 6)
Diseases named in the same sentence as IL6 in open-access papers (continued):
Sharing a sentence is not in itself a finding about the gene and the disease.
kidney injury (continued). "Although novel, sensitive biomarkers for KI have emerged quickly, such as IL6, cystatin C, kidney injury molecule-1, NGAL, urine vanin-1, and liver fatty acid-binding protein, BUN and Scr are still the most utilized biomarkers to assess kidney injuries in experimental animal models." (PMID 32630021, 2020). "Interestingly, some of the drivers for group separation (i.e., Tnfa, Ccl2, Il6, Lcn2, and UACR) were not significantly different between any of the four mouse groups when analyzed in isolation, but are widely known indicators of kidney injury." (PMID 34835482, 2021).
meningioma (21 papers, 2013 to 2025). A generally slow growing tumor attached to the dura mater. "The plasma fibrinogen is linked to the interleukin-6 gene promotor, and this laboratory parameter might be induced by the IL-6 secretion of meningioma cells." (PMID 35453901, 2022). "Therefore, interleukin-6 secretion is inversely correlated with the growth velocity of meningiomas and both serum CRP and plasma fibrinogen are linked to the promotor of the interleukin-6 gene." (PMID 35205781, 2022). "Plasma fibrinogen and serum C-reactive protein are both linked to the interleukin-6 gene promoter, and those parameters may be induced by the autocrine secretion of interleukin-6 by meningioma cells." (PMID 34298854, 2021). "This association might be explained by the secretion of interleukin-6 by human meningioma cells and an autocrine inhibitory regulation of neoplastic cell growth." (PMID 34298854, 2021). "Those most investigated with respect to seizures and meningioma include IL‐1ra, IL‐1β, IL‐6, IL‐10, IFN‐γ, and TNF‐α." (PMID 40729436, 2025). "When considering different meningioma subtypes, it is evident from the results that the patient with clear cell meningioma have higher levels of IL-6 compared to the other types." (PMID 38259646, 2023). "It has been found that human meningioma cells are capable to secrete IL-6 which can act as an autocrine inhibitory regulator of the growth of neoplastic cells." (PMID 34829359, 2021). "Using cell culture techniques, it was identified that human meningioma cells are capable of secreting interleukin-6, and the rate of interleukin-6 secretion had an inverse correlation with the growth rate of meningiomas." (PMID 34298854, 2021). "Those pathophysiological pathways enable the secretion of CRP in hepatocytes by induction of IL-6 secreted by meningiomas." (PMID 34829359, 2021). "Cytokines were also secreted when meningioma cells were challenged with the closely related organism N. lactamica, but levels of IL6 were significantly lower when cells were infected with N. lactamica." (PMID 33233688, 2020). "Among them, the NF-κB/hsa-miR-98-5p/IL6 coregulation pair is predicted to be most relevant to the pathogenesis of meningioma." (PMID 32832554, 2020). "It was furthermore shown that upon meningococcal infection meningioma cells specifically secrete pro-inflammatory (IL-6), chemotactic (IL-8, MCP-1, and RANTES), and growth factor-related (GM-CSF) cytokines." (PMID 33233688, 2020). "Meningiomas are believed to develop from meningiothelial cells that have several functions, including participating in immune response and IL6 secretion." (PMID 28903425, 2017). "For example, Interleukin-6, which could be produced by meningioma, might increase the production of platelet and facilitate tumor angiogenesis, which might be associated with significant IBL." (PMID 37682850, 2023). "Conversely, anti-IL-6 antibodies can enhance the tumor growth rate in meningiomas." (PMID 35453901, 2022). "This inverse association between plasma fibrinogens and an increased or increasing MIB-1 index in cranial meningiomas might be explained by the potential autocrine secretion of interleukin-6 (IL-6) by human meningioma cells." (PMID 35453901, 2022). "It was found that interleukin-6 acts as inhibitory on the growth of meningioma cells." (PMID 35453901, 2022). "Furthermore, the addition of an anti-IL-6 antibody enhanced the growth-stimulating effect of meningiomas." (PMID 34298854, 2021). "The function of IL-6 in meningioma seems to be ambiguously as it might enhance tumor growth in approximately 60% of tumors, whereas other investigations found an inhibitory role on proliferative activity of neoplastic cells." (PMID 34829359, 2021). "An overexpression of interleukin-6 is highly debated as it potentially might act as stimulating growth in approximately 60% of meningiomas, whereas it was also found to be an inhibitor of neoplastic cell proliferation as well." (PMID 34298854, 2021).
meningioma (continued). "Additionally, the administration of anti-IL-6 antibodies resulted in an enhancement of the growth of meningiomas." (PMID 34829359, 2021). "Meningioma cells were demonstrated to react to cAMP or cAMP-elevating agents with a decrease in cell growth rate, an effect partly mediated via the secretion of interleukin 6, which acts as an inhibitory factor." (PMID 31671850, 2019). "We hypothesize that IL6 secretion from meningioma cells could be involved in the tumorigenesis of meningiomas." (PMID 28903425, 2017). "The simple association between quick-to-use biomarkers such as serum CRP and tumor growth in meningiomas might be explained by the capability of human meningioma cells to secrete interleukin-6, which has an autocrine inhibitory role in the regulation of neoplastic cell growth." (PMID 35205781, 2022). "Hence, patients with a low plasma fibrinogen level might have a reduced autocrine IL-6 secretion by the meningioma cells, resulting in an increased tumor growth rate and proliferative potential." (PMID 35453901, 2022). "Furthermore, NF-κB/IL6, PTGS2, MYC/hsa-miR-574-5p, hsa-miR-26b-5p, hsa-miR-335-5p, and hsa-miR-98-5p, which are involved in the transcription factor-miRNA-mRNA coregulation network, were found to be associated with meningioma." (PMID 32832554, 2020). "Some cytokines such as IL‐6, CXCL12, and TGF‐β are expressed in an autocrine manner within meningioma cells, which are otherwise involved in a signaling mechanism and tumor behavior." (PMID 40729436, 2025). "The levels of the cytokines IL-6, IL-10, and GM-CSF, as well as the levels of the chemokine CCL2, were analyzed in the plasma of 27 patients with meningiomas (since one case had an undetermined subtype)." (PMID 38259646, 2023). "Cytokines such as interleukin-6 can simulate substances such as VEGF-A and MMP-9, which are involved in the pathogenesis of peritumoral edema in meningioma." (PMID 34298854, 2021). "Some cytokines/chemokines, e.g., IL-6, CXCL12 and TGF-ß, show a formation of autocrine loops in meningioma cells." (PMID 34503077, 2021). "While TGF-ß, IL-6 and OSM inhibit meningioma cell growth, SDF-1 and CXCL16 increase proliferation in cultured meningioma cells." (PMID 34503077, 2021). "cBioportal data confirmed high IL6 expression in meningioma patients correlated with tumour recurrence, unlike other macrophage-related cytokines." (PMID 40420192, 2025). "Overall, IL-6 may serve as a specific target to modulate the TME and improve meningioma treatment outcomes." (PMID 40420192, 2025). "Theories on the development of meningiomas and PBE also include multiple molecular factors such production of vascular endothelial growth factor (VEGF), and interleukin-6 expression, but further research needs to be done to understand the clinical behavior of these tumors." (PMID 35884624, 2022). "Additionally, we investigated the presence of miR-21 and the different cytokines: Interleukin-6 and Interleukin-10 (IL-6 and IL-10), Granulocyte-Macrophage Colony-Stimulating Factor (GM-CSF) and Chemokine (C-C motif) Ligand 2 (CCL2) in the plasma of 28 patients diagnosed with meningioma." (PMID 38259646, 2023).
metastatic prostate carcinoma (21 papers, 2004 to 2024). A carcinoma that arises from the prostate gland and has spread to other anatomic sites. "Elevated IL-6 levels are associated with hormone-refractory and metastatic prostate cancer." (PMID 39554609, 2024). "However, two phase II trials which employed siltuximab as second-line therapy for patients with metastatic prostate cancer showed an increase in plasma IL-6 after treatment and confirmed the poor prognosis associated with elevated IL-6." (PMID 33322216, 2020). "As an example, a recent study found that Proteobacteria was enriched in patients with metastatic prostate cancer and was positively correlated with plasma IL6 level, regional lymph node metastasis status, and distant metastasis status." (PMID 36286051, 2022). "Circulating levels of two proinflammatory cytokines, interleukin 6 (IL-6) and 8 (IL-8), have been found to be higher in hormone refractory and sensitive metastatic prostate cancer patients with poor prognosis, respectively." (PMID 34638258, 2021). "High levels of circulating IL-6 and IL-8 are biomarkers for severe metastatic prostate cancer in humans, and relative levels of these immune mediators are considered to be surrogates for tumor burden." (PMID 31428571, 2019). "Levels of IL-6 are elevated in the serum of patients with hormone-refractory and metastatic prostate carcinoma." (PMID 25261365, 2014). "When patients with metastatic prostate cancer were compared with both groups of patients with localised prostate cancer, there were significant differences in IL-6 and TNF-α levels among the groups." (PMID 15150588, 2004). "Indeed, serum IL-6 levels in patients with metastatic prostate cancer were higher than those in patients with localized prostate cancer." (PMID 28783760, 2017). "The levels of IL-6 are elevated in sera of patients with metastatic prostate cancer." (PMID 24282788, 2013). "Finally, 16S rRNA sequencing of patients’ fecal samples revealed that Proteobacteria was enriched in patients with metastatic prostate cancer and was positively correlated with plasma IL6 level, regional lymph node metastasis status, and distant metastasis status." (PMID 35710492, 2022). "In conclusion, viewed in the context of similar observations made for other cancers, these data further support a relationship between elevated IL-6 and TNF-α levels and metastatic prostate cancer." (PMID 15150588, 2004). "Our studies indicate that immune markers, such as IL-6 levels or the frequency of effector T cells, may be predictive of the outcome of treatment with ADT therapies in patients with metastatic prostate cancers." (PMID 31013891, 2019).
non-Hodgkin lymphoma (21 papers, 2006 to 2025). Distinct from Hodgkin lymphoma both morphologically and biologically, non-Hodgkin lymphoma (NHL) is characterized by the absence of Reed-Sternberg cells, can occur at any age, and usually presents as a localized or generalized lymphadenopathy associated with fever and weight loss. "A number of studies have evaluated the association between specific polymorphisms of IL-6 and IL-10 genes and the risk of non-Hodgkin lymphoma." (PMID 32046104, 2020). "Multiple pro-inflammatory cytokines have a principal role in lymphomagenesis: interleukin (IL) 6 (IL-6) is related to Th17 immune response that has association with non-Hodgkin lymphoma (NHL)." (PMID 35439998, 2022). "Non-Hodgkin's lymphoma was analyzed separately, finding significantly raised levels of IL-6 (AUC = 0.92) in this disease." (PMID 37114211, 2023). "IL-10, as IL-6, is a growth factor for non Hodgkin's lymphoma and is often correlated to a poor prognosis." (PMID 19956602, 2009). "The correlation between plasma IL-6 and IL-10 levels was also demonstrated in patients with non-Hodgkin's lymphoma and post-transplant lymphoproliferative disorder." (PMID 16995954, 2006). "Furthermore, IL-6 can induce MMP-9 expression in human malignant non-Hodgkin’s lymphomas, and IL-8 can induce MMP-9 expression in human neutrophils through activation of the CXCR2 receptor." (PMID 30423938, 2018). "Non-Hodgkin lymphoma (NHL) patients with high levels of serum interleukin-6 (s-IL6) and serum vascular endothelial growth factor (s-VEGF) have poor prognosis and shorter survival time." (PMID 25805671, 2015). "Studies show that tocilizumab, an interleukin-6 blocking therapy, resulted in rapid recovery from CRS in patients with aggressive non-Hodgkin lymphoma treated with CAR-T." (PMID 39089933, 2024). "In addition, plasma levels of CXCL13, IL-6 and IL-10 were potential markers for treatment outcomes and survival of patients with AIDS-associated non-Hodgkin lymphoma (NHL)." (PMID 33732259, 2021). "For instance, increased IL-6, IL-8, IL-1β, and TNF-α can induce MMP-9 expression in malignant non-Hodgkin’s lymphoma, human neutrophils, and corneal epithelial cells respectively." (PMID 30423938, 2018).
pericarditis (21 papers, 2012 to 2025). An inflammatory process affecting the pericardium. "Prior studies focused on the ligand (IL-6) and demonstrated that global Il-6 knockout and IL-6 pharmacologic inhibition protected against poAF in rat sterile pericarditis models." (PMID 40048254, 2025). "Interleukin-6 is a key cytokine in the pathogenesis of pericarditis, acting synergistically with IL-1 to drive inflammation and acute phase responses." (PMID 41210896, 2025). "In the atorvastatin and pericarditis groups, the serum levels of IL-6 and TNF-α were significantly increased 12 h after surgery (P<0.05), peaked 48 h after surgery and were significantly higher compared with the levels in the control group (P<0.05)." (PMID 25524260, 2015). "In the atorvastatin and pericarditis groups, serum levels of IL-6 and TNF-α gradually decreased, but remained higher than at the preoperative stage, even following the 21 day endpoint (P<0.05)." (PMID 25524260, 2015). "The levels of CRP were significantly elevated in the children with pericarditis (21.6 ± 13 mg/dL vs. 13.9 ± 11 mg/dL, p = 0.035), and the serum levels of IL-6 were higher in the children with small pericardial effusion compared to those without (191 ± 53 ng/L vs. 88 ± 27 ng/L, p = 0.041)." (PMID 38138278, 2023). "A possible differential diagnosis could be made using cytokine signatures in pericardial fluid, where high tumour necrosis factor (TNF)α and low transforming growth factor (TGF) β1 levels correlate with viral pericarditis, whereas a low IL-6 concentration with autoreactive pericarditis." (PMID 39798014, 2025). "The pro-inflammatory effects (increase in CRP and IL-6) and oxidative stress (MPO and ROS) intrinsic to ablation have been connected to early AF recurrence and pericarditis." (PMID 39156919, 2024). "In the patients with pericarditis, the serum levels of CRP were elevated significantly, and IL-6 was increased dramatically in our cohort of MIS-C children with small pericardial effusion compared to those without." (PMID 38138278, 2023). "However, lower levels of hs-CRP, IL-6 and TNF-α were observed in the atorvastatin group compared with the untreated pericarditis group (P<0.05)." (PMID 25524260, 2015).
postmenopausal osteoporosis (21 papers, 2014 to 2025). Metabolic disorder associated with fractures of the femoral neck, vertebrae, and distal forearm. "The ROC curve determined diagnostic values of circulating IGFBP-3 and IL-6 levels for postmenopausal osteoporosis." (PMID 37035758, 2023). "Studies have implicated that postmenopausal osteoporosis is partially mediated by the release of pro-inflammatory factors due to estrogen withdrawal, such as IL-6, TNF-α, and IL-1." (PMID 33628184, 2020). "Tetrahydrocoptisine was found to modulate postmenopausal osteoporosis by directly interacting with disease-related proteins such as IL6, IL1B, and TNF, in addition to affecting disease-associated biological functions and indirectly interacting with other disease-related proteins." (PMID 39596387, 2024). "In addition, the potential diagnostic role of circulating IGFBP-3 and IL-6 in the pathogenesis of postmenopausal osteoporosis in postmenopausal women was investigated." (PMID 37035758, 2023). "An analysis of ROC curves showed that circulating levels of IGFBP-3 and IL-6 could be identified as reliable diagnostic biomarkers for postmenopausal osteoporosis." (PMID 37035758, 2023). "This evidence suggests that postmenopausal osteoporosis is associated with IL-6." (PMID 37035758, 2023). "In addition, estrogen loss resulted in an IL-6-mediated stimulation of osteoclastogenesis, which suggests a mechanism for the increased bone resorption in postmenopausal osteoporosis." (PMID 24670840, 2014). "Bazedoxifene, originally approved by the FDA for managing postmenopausal osteoporosis as part of the combination therapy Duavee with conjugated estrogens, has also been identified as a novel inhibitor by blocking IL-6 and GP130 interaction." (PMID 41148817, 2025). "Xiao similarly observed efficacy during the use of Bazedoxifene, an FDA-approved agent with known anti-IL6:GP130 axis activity currently used to prevent postmenopausal osteoporosis." (PMID 40961077, 2025). "Inflammatory cytokines such as TNF‐α, IL‐1β and IL‐6 are elevated in postmenopausal osteoporosis and have been shown to play a role in the development of the disease." (PMID 38748896, 2024). "The potential role of IGFBP-3 and IL-6 in the diagnosis of postmenopausal osteoporosis was predicted using the area under the receiver operating characteristic curve (ROC, AUC)." (PMID 37035758, 2023). "The effects on bone loss observed with anti-IL-17A therapies in animal models of postmenopausal osteoporosis raised the question of a specific effect of this cytokine on the bone compared to other proinflammatory cytokines such as TNF-alpha or IL-6." (PMID 31485194, 2019). "In postmenopausal osteoporosis, bone resorption is also increased by the production of monocyte-related cytokines, such as IL-1, IL-6, and TNF-α, which induce RANKL expression in bone tissue and enhance RANKL-RANK-mediated osteoclastogenesis." (PMID 29348535, 2018). "We have identified Bazedoxifene, a Food and Drug Administration (FDA)-approved drug used for the prevention of postmenopausal osteoporosis, with novel function as inhibitor of IL-6/GP130 interaction." (PMID 28672024, 2017). "We have identified that bazedoxifene (BZA), a Food and Drug Administration (FDA)-approved drug used for the prevention of postmenopausal osteoporosis, when combined with conjugated estrogens in Duavee, also has a novel function as an inhibitor of IL-6/GP130 interaction." (PMID 39451730, 2024). "Both falcarindiol and tetrahydrocoptisine demonstrated direct interaction with pro-inflammatory cytokines IL6, IL1B, and TNF, key drivers of osteoclastogenesis and bone resorption in postmenopausal osteoporosis by activating inflammatory pathways linked to bone loss." (PMID 39596387, 2024). "Circulating measurements of IGFBP-3 and IL-6 might be essential predictors of postmenopausal osteoporosis and could predict osteoporotic fracture." (PMID 37035758, 2023).
postmenopausal osteoporosis (continued). "Circulating IGFBP-3 and IL-6 might be essential predictors of postmenopausal osteoporosis and can help predict osteoporotic fracture." (PMID 37035758, 2023). "In addition, IL-6 is regarded as a key factor of postmenopausal osteoporosis due to its ability to activate osteoclast and induce bone resoption." (PMID 27128729, 2016). "Therefore, postmenopausal osteoporosis is significantly impacted by IL-6." (PMID 37035758, 2023). "The direct interactions of rutin, beta-sitosterol, quercetin, norisoboldine, and hyperoside with key disease-related proteins such as TGFB1, TNF, IL1B, IL6, and CAT suggested that these compounds may modulate critical pathways involved in the pathology of postmenopausal osteoporosis." (PMID 39596387, 2024).